EGFR (epidermal growth factor receptor)
Diseases named in the same sentence as EGFR in open-access papers (continued):
Sharing a sentence is not in itself a finding about the gene and the disease.
tumor (continued). "Among the five diagnosis double minutes, dm1 has the same structure as dmIII in the relapse tumor except that dm1 carries EGFRvIII as evidenced by the deletion of seg14, which leads to EGFR exon 2–7 deletion." (PMID 30267146, 2019). "The analysis of circulating tumor DNA (ctDNA) is a valuable approach to monitor the clonal evolution of tumors during treatment with EGFR-tyrosine kinase inhibitors (TKIs) and to detect resistance mutations." (PMID 31039766, 2019). "The most common variant is EGFR variant III (EGFRvIII), which is a key marker for tumor-initiating cells." (PMID 31013819, 2019). "In the presence of hotspot mutants R175H and R273H, increased recycling of EGFR and integrins by enhanced binding of RAB-coupling proteins to endosomes result in relocalization of EGFR to the plasma membrane and promotion of tumor growth and invasion." (PMID 31861395, 2019). "EGFR is often overexpressed in human cancer cells, which correlates with tumor progression and worse prognosis for patients." (PMID 31649529, 2019). "Conjoint analysis of the expression pattern and prognosis roles of hub genes demonstrated the oncogenic effect of EGFR and tumor suppressive effect of PPP3CB and MYO5A in GBM." (PMID 30971889, 2019). "Both vascular targeting drugs and EGFR inhibitors were designed to enhance sensitivity of tumor cells upon radiation." (PMID 31426614, 2019). "In consequence of this and with the goal of blocking tumor neovascularization, we opted to use EGFR-TKIs." (PMID 30608421, 2019). "Several studies have shown that NF-kB activation drives survival of tumor cell treated with EGFR-TKIs." (PMID 30935067, 2019). "ERRFI1 is known as a tumor suppressor by directly inhibiting the epidermal-growth-factor-receptor and, therefore, its downstream pathways initializing cell growth." (PMID 30641895, 2019). "Numerous studies have highlighted the importance of optimizing the protein dose when targeting EGFR in order to partially saturate endogenous EGFR expression in the liver and, subsequently, increase the tumor uptake." (PMID 30213849, 2019). "Although demonstrated for EGFR, this proposed technique can be used for margin assessment to any highly specific targeted-imaging agents, provided the expression of the target in tumor tissue is vastly different from that of normal tissue." (PMID 31998640, 2019). "Treatment with IgA anti-HER2 or IgA anti-EGFR anti-tumor mAbs resulted in significantly enhanced anti-tumor cytotoxicity in FcαRI transgenic mice compared to WT littermates, which was mediated by FcαRI-expressing macrophages." (PMID 30984170, 2019). "EGFR expression levels were positively associated with the ACTH and cortisol levels and with tumor recurrence status." (PMID 31798535, 2019). "With EGFR, findings are conflicting, with some studies predominantly showing high FDG uptake in EGFR-mutated tumours, reflecting increased glycolysis through AKT signalling, and others showing lower uptake." (PMID 31190176, 2019). "We induced the EGFR-Pcn tumor in Dpp:mCherry flies, and labeled the EGFR-Pcn tumor cells with CD8:GFP." (PMID 31568500, 2019). "Proliferation IC50 values were <160 nM in tumor cell line models of EGFR and HER2 overexpression, 100-fold less than observed with cell line models of normal tissue." (PMID 31141894, 2019). "During EGFR-TKIs treatment, the EGFR mutant tumor cells are inhibited, whereas the EGFR wild-type tumor cells continue to proliferate." (PMID 31014278, 2019). "Meanwhile, we also observed similar results in NSCLC cells that express activating mutation-possessed EGFR, as knockdown of SHCBP1 remarkably suppressed tumor sphere formation capacity as well as activation of β-catenin signaling." (PMID 30177836, 2019). "Transfection of tumor cells with miRNA-145 led to a marked time-dependent reduction of EGFR mRNA level (p<0.05; relative to the blank control)." (PMID 31554377, 2019).
tumor (continued). "Our findings support the notion that in this population of patients from the real-world setting response to anti-EGFR agents and prognosis are significantly influenced by tumor sidedness." (PMID 31762802, 2019). "It was recently shown that squamous cancer cells activate EGFR in response to tumor stiffness, which leads to actomyosin contractility and collective invasion." (PMID 31067787, 2019). "We also did the immunohistochemistry analysis of these metabolic enzymes in a panel of NSCLC PDX tumor tissues with mutant EGFR (n = 6) or wildtype RTK (n = 6)." (PMID 31221965, 2019). "We found that EGFR has the highest degree among all the miRNA-target genes, which further validates its essential role in tumor progression and metastasis." (PMID 31032340, 2019). "In a HNSCC heterotopic xenograft tumor model, treatment with the epidermal growth factor receptor (EGFR) blocker Cetuximab inhibits angiogenesis by downregulating Notch1 and Hypoxia-inducible factor 1 alpha (Hif1α) subunit." (PMID 30917608, 2019). "For example, the treatment with 5-fluorouracil (5-FU), often combined with anti-EGFR Abs, results in M1 polarization of the macrophages fostering anti-tumor activity both in vitro and in vivo." (PMID 31370270, 2019). "Recently, endogenous ligands such as epidermal growth factor (EGF) have shown great potential for targeting EGFR on tumor cells." (PMID 31754382, 2019). "We therefore decided to synthesize fluorescein labeled SiO2-NPs tagged with anti-EGF-receptor-antibodies (EGFR-SiO2-NPs) and evaluated this novel contrast agent for tumor specific targeting in an ex vivo model system." (PMID 31561451, 2019). "Patients with gene mutations in the tumor had a shorter survival time than patients with the wild type gene, except for NRAS, BRAF, and EGFR mutations." (PMID 31255173, 2019). "We wondered if EGFR-engineered CD8+ lymphocytes would exhibit an enhanced therapeutic effect in vivo in tumor-bearing mice." (PMID 31921216, 2019). "Specific receptors that are highly expressed in tumors and on the surface of tumor endothelial cells include transferrin receptor, folate (FA) receptor, integrin receptor, somatostatin receptor, lectin receptor, and epidermal growth factor receptor (EGFR)." (PMID 31915707, 2019). "The defining characteristic of the third-generation EGFR TKIs is that they have significantly greater activity against EGFR mutant receptors than EGFR wildtype (WT), making them more sensitive for tumor cells." (PMID 31134065, 2019). "A variation on targeting EGFR is targeting EGFRvIII (de2-7 EGFR), a tumor-specific receptor produced by 801 bp in-frame deletion of the EGFR nucleotide sequence through alternative splicing." (PMID 31681205, 2019). "This EGFR inhibitor demonstrated to have antitumor activity in-vitro and also in tumor xenograft mouse models." (PMID 31370258, 2019). "Our data suggest that sensitization of tumor cells by anti-EGFR TKIs differentially modulates interactions with NK cells." (PMID 31546690, 2019). "The tumor uptake levels of [111In]In-DOTA-cetuximab in EGFR-positive xenografts were significantly higher than that of EGFR-null H520 tumors (P < 0.05)." (PMID 31651282, 2019). "Neutrophils are superior at eliminating IgA-opsonized tumor cells compared to IgG using EGFR, CD20, HER2 and HLA II as targets in in vitro studies." (PMID 31031746, 2019). "Emergence of EGFR mutations following radiation and temozolomide treatment of GBM indicates that dysregulated EGFR signaling can contribute to late expansion of tumor." (PMID 30267146, 2019). "Examples of tumor targets are the typical tumor-related receptors EGFR and HER2, although the interleukin-2 receptor and carcinoembryonic antigen have also been used as valuable tumor biomarkers." (PMID 31544832, 2019). "More importantly, DCD has been considered as biomarker for cellular resistance of various tumor cells to the EGFR/ErbB1 tyrosine kinase inhibitors erlotinib and lapatinib." (PMID 35582587, 2019).
tumor (continued). "While several mechanisms of acquired EGFR-TKI-resistance have been determined by analyzing tumor specimens obtained at disease progression, the factors causing intrinsic TKI-resistance are less understood." (PMID 31266248, 2019). "More importantly, β-catenin localization and tumor progression also positively fed back on EGF/EGFR-attenuated AJAP1 expression." (PMID 31171012, 2019). "When compared with matched tumor tissues (n = 31), EGFR detection using exosomes showed sensitivity of 100% (10/10), specificity of 95.24% (20/21) and concordance rate of 96.77% (30/31, Kappa = 0.928, P < 0.001)." (PMID 31608233, 2019). "The findings suggest that miRNA inhibits NSCLC tumor growth and metastasis through targeting of EGFR." (PMID 30984273, 2019). "It would be of interest to test EGFR-targeted PDT in organoids derived from a tumor carrying EGFR amplification, to see if responses are comparable to those observed in the organoids reported here." (PMID 31694307, 2019). "The expression levels of CDK6 and EGFR were further observed in GC and their matched adjacent non-tumor tissues of 40 patients by immunohistochemical staining followed by the correlation analysis of the expression levels of the two proteins and miR-1296-5p." (PMID 30530570, 2019). "In the EGFR (+) group, 60.1% of patients were female, 94.1% of them had tumor stage IV and 16.8% of them had smoking history." (PMID 31419239, 2019). "Whereas EGFR gene amplification and activating mutations in the receptor kinase domain are frequent in human CRC samples, experiments in mice showed that the EGFR activity is indispensable for tumors developed in Apc+/Min mice or in AOM/DSS-induced neoplasia." (PMID 31614493, 2019). "DESC1 is an epithelial-specific enzyme and exerts tumor suppressive roles by promoting cell apoptosis via the downregulation of the EGFR/AKT pathway in ESCC." (PMID 30223861, 2018). "As an important signaling pathway downstream of EGFR, AKT is associated with tumor cell survival, proliferation, and invasiveness." (PMID 29861842, 2018). "Consistent with our previously reported observations in lung metastases, these lymph node metastases display increased resistance to the EGFR inhibitor erlotinib as compared to primary tumor NME cells when cultured under 3D organotypic conditions." (PMID 30250119, 2018). "EGFR mutant allelic fraction was also measured on tumor and plasma samples by 6-color digital PCR, and displayed a highly significant correlation with next generation sequencing and 3-color digital PCR." (PMID 30647840, 2018). "To assess the integrity of the tumor microenvironment during histoculture, we performed additional immune stainings on the same sections previously selected for EGFR." (PMID 29861851, 2018). "Immunohistochemistry of tumor tissue is the most clinically used method to detect EGFR at protein level." (PMID 30393665, 2018). "The T4 tumor also harbors the L858R/T790M and the patient progressed on osimertinib (or AZD929), a third-generation EGFR inhibitor that targets the T790M mutation." (PMID 29651165, 2018). "Images after 1 and 6 hours’ incubation showed increased signal intensity in the EGFR-positive tumor cells." (PMID 29856819, 2018). "For example, cetuximab (C225)—an effective chimeric monoclonal antibody—has been used in clinical cancer treatments that target human EGFR and inhibits EGFR-dependent primary tumor growth and metastasis." (PMID 29470420, 2018). "The aberrant fucosylation of tumor is always involved in the activation of EGFR or TGF-βR, and affect the function of integrins, selectins, and apoptotic signaling pathways; ultimately influencing tumor proliferation, invasion, apoptosis, and metastasis." (PMID 30619732, 2018). "Anti-EGFR anchored PTX loaded nanoparticle is very effective to reduce TNBC tumor volume in the Xenografts animal model." (PMID 30408068, 2018). "On the other hand, HIF signaling can also activate the EGFR pathway, potentiating survival and tumor growth." (PMID 29603584, 2018).
tumor (continued). "Our results of high EGFR on human tumor EC-like cells from GBM39 is also consistent with results of clinical GBM samples." (PMID 30050899, 2018). "Standard in vitro assays are limited to the evaluation of the anti-EGFR response in either human tumour models or skin equivalents, each in a separate conventional static tissue culture." (PMID 30301942, 2018). "PD-L1 and PD-1 interaction is among the signals beneficial for tumor cells, which also include EGFR signaling, CD 28 stimulation and many others." (PMID 30547012, 2018). "The most frequently mutated genes across all tumor types included KRAS, PIK3CA, BRAF, EGFR, NRAS and ERBB2." (PMID 29854313, 2018). "In conclusion, VEGF or EGFR plays an important role in regulating the pivotal switch of BM in tumor angiogenesis." (PMID 29992751, 2018). "Volumetric reduction and metabolic 18F-FDG uptake change were evaluated in high-EGFR-expressing TE-8 tumor model." (PMID 30373221, 2018). "The quest for a potent and efficient therapy led to the development of bispecific antibodies or fragments to target more than one molecular signature (tumor associated antigens) amplified in lesions, e.g., EGFR/IGF1-R38, EGFR/Met39, and HER2/HER340." (PMID 29899472, 2018). "The inclusion criteria were RCT (randomized controlled trials) studies that evaluated the efficacy of anti-EGFR mAbs based on primary tumor location." (PMID 30296945, 2018). "The recent emergence of acquired resistance to “third-generation” EGFR tyrosine kinase inhibitors (TKIs) via multiple mechanisms serves to illustrate the important influence of tumor heterogeneity on prognostic outcomes in patients with NSCLC." (PMID 29632655, 2018). "It was documented that EGF and its receptor EGFR are frequently overexpressed in many forms of RCC, and signaling cascade through EGF/EGFR/STAT3 play an important role in tumor cell growth and EMT in RCC33,35,46." (PMID 29717134, 2018). "Anti-EGFR conjugated cerasomes demonstrated enhanced internalization in highly EGFR expressed cancer cells thereby resulting in effective inhibition of tumor growth." (PMID 29721494, 2018). "Second, high pre‐treatment levels of ctDNA, and specifically of EGFR mutations in plasma prior to treatment with EGFR‐TKI, correlated with increased tumour burden and were associated with poor prognosis, echoing previous findings." (PMID 29848757, 2018). "In clinical practice, the EGFR status of tumor tissues can be assessed using immunohistochemistry (IHC), which only provides limited information on target expression due to heterogeneity." (PMID 30373221, 2018). "In the present work, BetA's anticancer activity against drug-resistant tumor cell lines was studied, in which either MDR-conferring ABC-transporters (P-glycoprotein, BCRP, and ABCB5) or mutation-activated EGFR were overexpressed." (PMID 29867487, 2018). "Recently, it has been also reported that the inhibition of the EGFR signaling pathway facilitates the activation of immune cells and their recruitment to tumor sites via the production of several cytokines and chemokines." (PMID 29892573, 2018). "This CAR, based on the monoclonal antibody cetuximab, is less efficient in targeting EGFR-expressing tumor cells than EGFRvIII-positive cells." (PMID 29685162, 2018). "EREG and AREG levels have been shown to predict tumor response and disease control in patients treated with EGFR-antibodies in both, RAS or KRAS exon 2 wild-type populations." (PMID 30467535, 2018). "Four RCTs evaluated the efficacy of anti-EGFR mAb plus chemotherapy versus chemotherapy alone by tumor location, including a study in the context of a chemotherapy triplet of FOLFOXIRI." (PMID 30296945, 2018). "For in vivo PDXs, afatinib also exhibited the greatest anti-tumor effects among the EGFR blockers, with a TGI of 100.22% for PDX03 and 82.65% for PDX06." (PMID 30157900, 2018).
tumor (continued). "Targeting moieties such as MoAbs, antibodies directed against carcinoembryonic antigens (CEA), transferrin, and EGFR also have been introduced on the surface of liposomes to specifically target tumor cells." (PMID 29914561, 2018). "In the TCGA study population, all tumours with either EGFR or HER2 gene amplification were observed to have intestinal-type histology." (PMID 29046940, 2018). "In this regard, several in vitro and in vivo models have shown that the masking of EGFR with a specific blocking monoclonal Ab (mAb) inhibits tumor proliferation, induces terminal cellular differentiation, and modulates chemo- and radio-sensitivity." (PMID 29892573, 2018). "Our data showed that EGFR-CAR T cells dramatically decreased tumor burden compared with those of PBS or UTD T cells (P < 0.001)." (PMID 29415996, 2018). "We harvested HPV38 and TC-1 tumours growing in mice, and examined the expression of EGFR in paraffin-embedded sections by immunofluorescence." (PMID 29552307, 2018). "In this study, A549 cell line and EGFR-mutant cell line PC-9 with higher expression level of Lyn than A549 cells were used to assess the anti-tumor effects of honokiol." (PMID 29892225, 2018). "As demonstrated by the TM titration experiments, 250-fold lower concentrations of the bivalent TM were able to activate UniCAR-armed T cells for tumor cell killing compared to the monovalent α-EGFR TM." (PMID 29876011, 2018). "Treatment with lapatinib, the inhibitor targeted on HER2 and EGFR reprogrammed the tumour microenvironment which favoured of cholangiocarcinoma cell growth suppression." (PMID 29455663, 2018). "In clinical settings, tumor DNA obtained from malignant tissue is the major source for EGFR genotyping while circulating cell-free DNA (cfDNA) can be used when biopsy is not feasible." (PMID 30647840, 2018). "The retargeting improves the tumor-to-liver ratio from 51 to 7200 and from 1000 to 10,000 for both the EGFR+ and HER2+ xenograft, respectively, after intratumoral injection." (PMID 29386504, 2018). "Repeated dose treatment of the anti-EGFR-antibody cetuximab showed an increased pro-apoptotic related gene expression in the tumour microtissues." (PMID 30301942, 2018). "We also observed EGFR amplifications in the metastasis sample of CRC-005 (4 copies) compared to the tumor (3 copies), implicating consequences for EGFR-based targeted therapy of certain metastases." (PMID 30429477, 2018). "In this report, we present such a patient who then received treatment with an epidermal growth factor receptor inhibitor, erlotinib, concurrent with a tumor-treating field device, Optune." (PMID 30410775, 2018). "Tumor cell growth and survival often depend on constitutively active signaling pathways such as epidermal growth factor receptor (EGFR) signaling." (PMID 30001368, 2018). "The EGFR status was known in the tumour of 43 of the 50 patients, and we detected the same EGFR mutation in any follow‐up plasma samples of 41 of 43 (95%) patients." (PMID 29848757, 2018). "The aim of this study was to analyze EGFR-dependent Akt and mTORC1 signaling in treatment-naïve tumor samples of the OSAG 101-BSA-05 patient cohort as a potential predictive biomarker of nimotuzumab efficacy." (PMID 30129426, 2018). "At cut off >5% of tumour cells with positive staining, 62%, 59%, 65% and 45% of the cases were EGFR, HER-2, HER-3 and HER-4 positive, and 3%, 22% and 48.3% of the cases were positive for EGFRvIII, c-MET, and CD44 respectively." (PMID 29731973, 2018). "Targeted approaches using fluorescent molecules that specifically bind cancer cells are needed to determine tumor margins and provide quantitative information about EGFR expression." (PMID 29464066, 2018). "High expression of EGFR and NGcGM3 was detected by immunohistochemistry assay on tumor biopsy before immune treatment." (PMID 29844873, 2018).